CD44 (CD44 molecule (IN blood group))
Diseases named in the same sentence as CD44 in open-access papers (continued):
Sharing a sentence is not in itself a finding about the gene and the disease.
tumor (continued). "CD44 and its ligand, hyaluronan (HA), are involved in the maintenance of stem cell properties of CRC cells by upregulating Snail expression through Src-mediated inhibition of miR-203, a tumor suppressor." (PMID 32456226, 2020). "For CD44 staining, 26 (92.9%; 4 weak, 8 moderate, 14 strong) of 28 MIBC tissues; 18 (85.7%; 7 weak, 9 moderate, 2 strong) of 21 NMIBC specimens; 11 (61.1%; 9 weak, 2 moderate) of 18 benign bladder tissue were positive." (PMID 32850423, 2020). "Studies have confirmed that CD44 is a nonkinase transmembrane glycoprotein that can promote tumor cell proliferation and invasion." (PMID 32908877, 2020). "Immunohistochemically, CD133, CD44, and nestin expression was positive in tumor cells regardless of cell size in GC-GBM, and there was no site-dependent propensity in MS-GBM." (PMID 31655917, 2020). "Primary sorted CD44+/EPCAM+ cells derived from a 74-year-old male patient, who underwent surgery for stage IIIA NSCLC, were cultured to assess the growth ability of these cells to form tumor spheres in vitro." (PMID 32391123, 2020). "HNC0014 alone significantly delayed the tumor growth and showed even better results when combined with the anti-PD-L1 antibody; this is conceivable since HNC0014 reduced CD44, β-catenin c-Met, and its phosphorylated form (c-Metp), all of which are contributors towards immune suppression." (PMID 33327484, 2020). "For example, in GBM, BSH-polyR appeared tumor-selective, because CD44 expression was not typically detected in normal brain." (PMID 32977522, 2020). "Similar to CD44, CD13 could combine with other surface markers, including CD133 or CD90, and effectively initiate tumor formation, leading to increased HCC tumorigenesis." (PMID 32466488, 2020). "Unlike CD44, the expression of the v6 isoform is relatively tumor-restricted with minimal expression on keratinocytes, activated T-cells and monocytes." (PMID 32850376, 2020). "Dormant tumor cells from the liver were recovered only from the FAC/AIT group 2–3 months after culture ex vivo (FAC/AIT L) and showed similar characteristics as MMC for the expression of neu, EpCAM, or predominant CD24+CD44+ fraction." (PMID 33115528, 2020). "The unique glycosylation of CD44 in MIBC patients may account for the tumorigenic and tumor progression processes, however further validations has to be carried out." (PMID 32922663, 2020). "CD44 extracellular domain contains binding sites for various ECM proteins such as collagen, laminin, and fibronectin, while hyaluronic acid (HA) produced both by tumor cells and tumor stroma is the main and most specific CD44 ligand." (PMID 32793493, 2020). "Previous studies demonstrated that CD44-positive GC cells displayed all basic CSC features and also chemo- and radio-resistance properties, which are likely to account for the resistance of this tumor type to most standard treatment protocols." (PMID 31973075, 2020). "In contrast, nonstemlike CD44- tumor cells have a significant intravasation ability that requires a certain epithelial–mesenchymal status (expression of N-cadherin)." (PMID 32316333, 2020). "The experiment results showed that the number of tumour stem cells (proportion of CD44+/CD133+ cells) and Tie1-positive cells in tumours originating from miR-485-5p@SPIONs-HuGSCs was significantly lower than that in those originating from miR-mut@SPIONs-HuGSCs." (PMID 32174801, 2020). "We observed a mixture of CD44-positive and CD44-negative CD8+ T cells within MOC2-luc tumor tissue, suggesting that these CD44-positive CD8 T cells may be depleted upon CD44-targeted NIR-PIT." (PMID 33322807, 2020). "Nonetheless, CD44+ CD8 T cells were found in MOC1 tumor tissues one week after combination of CD44-targeted NIR-PIT and CTLA4 mAb, which suggested that newly induced T cells were accommodated and operated anti-tumor immune activity to suppress tumor growth for MOC1 tumors." (PMID 32937841, 2020).
tumor (continued). "(G) FMI of polyclonal CD8+CD44+ T cells migrating towards tumouroids containing OT1 CTLs with cognate or non-cognate tumour cells." (PMID 33046212, 2020). "The percentage of CD44+CD62LlowT cells and Foxp3+T cells is comparable between in the dLNs of tumor-bearing mice treated by DMM or not." (PMID 32596169, 2020). "The level of CD44 mRNA was increased in the tumor parts rather than the adjacent nontumor tissues, and positively correlated with the level of CPAP mRNA in HCC." (PMID 31511651, 2020). "For CD44-negative Hep3B cells, a reduction in tumor volume was not obvious with GANT61 administration but obvious in the combination group." (PMID 31992334, 2020). "Functional interaction between CD44 and STAT3 can also occur at different levels of the TME, discussed in detail below, and encompass tumor endothelial cells, fibroblasts, and cells of the immune system, such as myeloid-derived suppressor cells, macrophages, and regulatory T and B cells." (PMID 33335857, 2020). "CD44 is required for Mdm2 nuclear translocation and AKT activation leading to tumor progression." (PMID 32984031, 2020). "For the other cores, CD44 stained a number of smaller, intra-lesional cells, interpreted to represent TILs, and negative in the actual tumour cells, with some vascular staining." (PMID 32245446, 2020). "More importantly, HNC0014 treatment significantly delayed tumor growth in a syngeneic mouse HNSCC model, elicited an antitumor immune profile, and reduced the total c-Met, STAT3, and their phosphorylated forms, PD-L1 and CD44, contents in serum exosomes." (PMID 33327484, 2020). "Tumor tissue in RT-R-MDA-MB-231-injected mice showed significant increases in the expression of CD44, Notch-4, and Oct3/4, but not ALDH1 in the present study." (PMID 33126606, 2020). "CD44 expressed on CTC was shown to interact with the HA coat produced by endothelial cells and initiate the process of tumor cell extravasation, particularly to the bone marrow, as shown in various tumor models through in vitro studies." (PMID 32793493, 2020). "Similarly, a study with thyme haulm showed a significant decrease in CD44 and ALDH1A1 expression in tumor tissues in rats." (PMID 32204409, 2020). "A greater level of CD44 cleavage and shedding may have occurred in EDW01 PDX tumours than ED03, facilitated by stromal MMPs, resulting in the observed heterogeneous pattern." (PMID 33276802, 2020). "For example, CD44 is known for its wide variety of functions including but not limited to lymphocyte activation, recirculation, hematopoiesis, and tumor metastasis." (PMID 32848883, 2020). "Tumor xenografts derived by the injection of purified HCT116- and HT29-CD133+CD44+ cells were digested to isolate CD133−CD44− and CD133+CD44+ cells, and 1 × 103 CD133+CD44+ cells or 5 × 107 CD133−CD44− cells from the first-generation xenografts were subcutaneously transplanted into secondary mice." (PMID 32729895, 2020). "However, a combination of CD44-targeted NIR-PIT and anti-PD-1 mAb was more effective compared to monotherapies with greater reduction of tumor progression, prolonged survival and an increased complete remission rate as high as 67%." (PMID 33322807, 2020). "We used tissue slides to study the expression of the RSK4, CD44 and MMP-9 proteins in human pRCC and mRCC tumour tissues by immunohistochemistry and found that the RSK4, CD44 and MMP-9 proteins were weakly expressed in pRCC and much more strongly expressed in mRCC tissues." (PMID 32209138, 2020). "Flow-cytometric analyses revealed significant alterations in the Lin-Thy1.2+ DN2, DN3, and DN4 subpopulations (CD25−CD44+c-Kit− DN1, CD25+CD44+c-Kit+ DN2, CD25+CD44−c-Kit− DN3, and CD25−CD44−c-Kit− DN4) isolated from the thymi of tumor-bearing mice vs. control tumor-free mice." (PMID 32582141, 2020). "At the same time CD44+ and CD44− tumor cells did not express BNIP3, while CD44− xenografts were enriched in CD31+ cells." (PMID 32214151, 2020).
tumor (continued). "Likewise, CD44, in combination with CD133 or CD24, is widely used to determine the CSC population in various tumor types." (PMID 32121074, 2020). "CD44 antigen is a receptor for hyaluronic acid and can interact with SPP1 and other ligands, allowing it to participate in a wide variety of cellular functions, including lymphocyte activation, recirculation and homing, hematopoiesis, and tumor metastasis." (PMID 33375642, 2020). "In addition, we confirmed that the expression levels of CD44 and ALDH1A3, markers of CSCs, in tumor organoids were significantly lowered after KYA1797K treatment." (PMID 32457491, 2020). "The histological analysis of MOC1 tumor one week after treatment showed that infiltration of CD8+ and CD4+ T-cells into the tumor bed dramatically increased after CTLA4 immune-checkpoint blockade alone and combined regimen of CD44-targeted NIR-PIT with CTLA4 immune-checkpoint blockade." (PMID 32937841, 2020). "Similar to the immunostaining results of tumor tissues from BC patients, TFCP2L1‐expressing cells in xenograft samples showed a high concurrence with cells stained with the bladder CSC markers including CD44, KRT14, and SALL4." (PMID 31709755, 2020). "The SRH cell line is derived from a mesenchymal tumor that is reflected by cell surface expression of mesenchymal markers, including CD10, CD44, CD73, CD90, CD105, CD146, and CD166 concomitant with the lack of the hematopoietic lineage surface markers CD14, CD19, and CD45." (PMID 33322555, 2020). "A non-kinase transmembrane proteoglycan, CD44 exerts its effects on tumor cells by modulating cytoskeletal architecture and activating various protein kinases or transcription factors." (PMID 32674318, 2020). "Flow cytometry analysis of protein expression profile of unmodified TMVs showed that TMVs express tumor and immune cell markers such as cancer stem cell markers (CD24 and CD44), co-stimulation (CD80 (B7-1)), immunosuppression (CD47, PD-L1), and innate immune cells (Gr1)." (PMID 32295135, 2020). "The innovation of CD44 and CD133 antibody-conjugated ATRA-loaded poly (lactide-co-glycolide)-lecithin-PEG NPs could specifically target CD44+ and CD133+ gastric CSCs, leading to the inhibition of tumor growth." (PMID 33321708, 2020). "Among these cell lines, HT29 cell line was highly expressed with FBX8, SOX-2 and SOX-2, and CD44, while quite weakly expressed with CDK4, HIF-1α, and c-Myc, indicating that HT29 cell line was an appropriate model to study tumor dormancy." (PMID 32796813, 2020). "Meanwhile, many kinds of tumor cells, such as breast cancerstem cells (BCSCs) and human non-small cell lung carcinoma (A549), over-expressed CD44 cellsurface marker." (PMID 31924103, 2020). "CD44, a nonkinase transmembrane receptor that mainly binds extracellular matrix hyaluronan (HA), is preferentially expressed in a variety of tumors, tumor-initiating cells, and drug-resistant tumor lesions." (PMID 33024087, 2020). "It is also important to note that we did not see an effect on early tumor formation within the MDA-MB-231 orthotopic transplant model when CD44 was deleted from the cancer cells." (PMID 32455980, 2020). "The reduction in CD44 levels in Sh5AC tumors was not as significant as in cell lines, possibly due to the mixed origin of lysate from both tumor and normal epithelial cells." (PMID 32098629, 2020). "In addition, some studies showed that ALDH1+CD44+ HNSCC cells expressed lower level of miR145 and thus inhibiting miR-145 has been adequate for driving the tumor-inducing characteristics in the ALDH1−CD44− HNSCC cells." (PMID 32280305, 2020). "CD44, a cell surface protein, has been previously shown to play an important role in cancer stem cell (CSC) function and driving the progression of several tumor types, including ovarian." (PMID 33335857, 2020).
tumor (continued). "Interestingly, we found a high frequency of CD44+/CD24− BCSCs in LIPH + TNBC tumours, where LIPH silencing decreased the ratio of CD44+/CD24− stem‐like cells in vitro and blocked their mammosphere‐forming ability." (PMID 32618099, 2020). "Low numbers of CXCR4+MET+CD44+ cells initiated tumor growth, while negative samples, with one exception, failed to do so." (PMID 32066735, 2020). "In the production of in vivo passages, we found that CD133+CD44+ cells did not lose their tumorigenic potential but instead had enhanced aggressiveness, as indicated by faster tumor growth and an increasing number of CD133+CD44+ cells in newly generated tumors." (PMID 32729895, 2020). "Previously we have constructed redox-responsive polymeric micelles composed of vitamin E succinate conjugated hyaluronic acid (HA-ss-TOS), which are able to actively target CD44 proteins and quickly release loaded drugs upon exposure to high levels of glutathione (GSH) in tumor cells." (PMID 31894722, 2020). "Following co-culturing of the tumor cells with CAFs, a process that has led to increased production of CXCL12, CXCR4 inhibition has reduced the formation of spheroids that were enriched with CD44+/CD24− cells." (PMID 32582148, 2020). "CD44 expression was highly responsive to ATRA as it was down regulated following treatment, and ATRA treatment also resulted in decreased migration and invasion of cancer cells and promoted tumor regression by inducing differentiation." (PMID 32293355, 2020). "CD44 did not affect survival based on tumor burden in Hs578T or MDA-MB-231 models, although onset was delayed within the Hs578T model." (PMID 32455980, 2020). "As the co-expression of ALDH1A3 with the stem cell marker CD44 was also found, we propose that ALDH1A3 positive tumor cells might possess the stem cell-like properties involved in tumor progression and therapy resistance." (PMID 32680476, 2020). "In addition, hyaluronic acid interactions with CD44 and RHAMM regulates tumor growth and metastasis." (PMID 32133350, 2020). "Furthermore, soluble CD44, CD44v6, CD44v8-10 and EpCAM were significantly increased in the recurrence group for early stage CCA; they also correlated with high levels of the tumor marker CA19-9." (PMID 32039729, 2020). "The results showed that, compared with the control group, CD24, CD44, N-Cadherin, β-catenin, and Vimentin in tumor tissues before NAC were significantly overexpressed, and CD24, CD44, E-cadherin, N-cadherin, β-catenin, and Vimentin were significantly lower expressed in paracancer tissues before NAC." (PMID 33282946, 2020). "It is worthy pointing out that both parental cells and tumor sphere cells were not homogenous because the labeling intensity differed markedly, such as the CD44 and CD24 fluorescent intensity." (PMID 31196164, 2019). "Conversely, ALM201 alone or in combination with tamoxifen demonstrated a substantial delay in tumour initiation and reduced the proportion of the CSC-like population assessed by ex vivo mammosphere assay, which correlates with the content of CD44+/CD24− CSC population." (PMID 30975104, 2019). "Of note, the immunosuppressive signature was most associated with the tumor subpopulation expressing the migration marker CD44 in PTEN-mutated tumors rather than Tregs, revealing a central role of PTEN-mutated tumor cells in immune regulation." (PMID 31658667, 2019). "It has been reported that the surface markers such as CD133, in combination with CD29/CD24 and CD44/CD166, may correlate with high Wnt activity and identify stem cells in various tumour types and their possible interaction with the microenvironment." (PMID 31511776, 2019). "We included CEP-IL as additional control in the in vivo experiment to see the role of CD44 antibody intrinsically, as the stated antibody bound to an empty liposome is able to improve the therapeutic efficacy and inhibit tumor growth even without cancer drug." (PMID 30818864, 2019).
tumor (continued). "Tumor progression and a pro-inflammatory TME that is conducive to metastasis is the result of activation of NF-κB and JNK signaling pathways, which are mediated by versican binding to CD44." (PMID 31323899, 2019). "We demonstrated that TGIF1 inactivation promotes KrasG12D-driven pancreatic tumorigenesis and that TGIF1 ablation has tumor-promoting effects and activates the HAS2/CD44 cancer stemness pathway, a potent regulator in the induction of TAM polarization, which enhances PDAC distant metastasis." (PMID 31109321, 2019). "The analysis of memory T cells at day 59 in an independent experiment revealed that most of the M2 specific T cells were effector memory (CD83+CD8+IFNγ+CD44+CD62LLO), thus suggesting that a boost in the immune response could further improve tumor protection." (PMID 30764846, 2019). "CD44 provides a surface docking station for active proteolytic MMP9; this specific localization at the cell membrane is required for MMP9’s ability to promote tumor invasion." (PMID 31810195, 2019). "Therefore, in this study using specific antibodies, we investigated the prognostic value of the co-expression of CD44, CD133, EGFRvIII, wtEGFR, and EGFR ligands in tumour specimens from 70 mCRC patients." (PMID 30899442, 2019). "The Gr-1+ dim/CD44+ dim immature myeloid cells have been reported to suppress T-cells and IFN-γ production, the dim expression intensity of these markers was characteristic to 4T1 tumor bearing mice." (PMID 31881770, 2019). "Whilst the ER status of BCSCs enriched in ER + ve tumor cells resistant to endocrine therapy is not clear, evidence suggests the ER-ve status of both CD44+CD24−/low and ALDH1+ BCSCs." (PMID 31336602, 2019). "The results of our study suggested the tumor-promoting effects of 3MC in hRECs; 3MC initiated EMT induction and induced cells to exhibit RCC features, including increased migration and invasion, colony formation, and CD44 expression." (PMID 30872677, 2019). "Our results demonstrated that overexpression of miR‐200c resulted in an obvious decrease in the number and diameter of tumour spheres formed from sorted CD44+CD24− phenotype SKBR3‐S but not MCF‐7‐S cells." (PMID 31599500, 2019). "While the tumor growth in this xenograft model was clearly dependent on the HA synthesized by the engineered stromal cells, there was no measurable effect when CD44 expression was abolished in tumor cells, the stromal cells, or the host." (PMID 31762938, 2019). "In addition, the percentage of CD44+ cells in GC06 is high, reaching about 50% of the tumor cells, as previously reported." (PMID 31010193, 2019). "The main advantage of this system was that it allowed us to experiment with different administration schemes and monitor the effects on the entire tumor cell population, as reflected in the number of tumorspheres, and on the CSC subpopulation (CD44+CD24-/low), as analyzed by FACS, at the same time." (PMID 31627418, 2019). "Using non-cytotoxic/non-cytostatic doses of IFN-β, we saw a significant repression of OSM- and TGF-β-induced stemness (reduced tumor sphere formation, migratory capacity, and a lack of CD44 induction)." (PMID 31036052, 2019). "When LAPC4 cells engineered to express miR-34a were injected into mice, we did not observe changes in tumor growth or CD44 expression; however, unexpectedly miR-34a expression was lost in vivo." (PMID 30860027, 2019). "Moreover, miR‐708 markedly inhibits sphere formation, CD44+/CD24− ratio, and tumour initiation and increases chemosensitivity of BCSCs." (PMID 31273952, 2019). "In addition, EpCAM, CD44, and CD24 have been reported to be relevant for tumor progression and metastatic processes." (PMID 31261643, 2019). "Both HO8910 CD44+CD117+ cell and ID8 cancer stem-like cell vaccinations provided significant protection against the tumor cell challenges and inhibited the growth of tumor cells as xenografts in nude mice or as allografts in C57BL/6 mice compared to the control vaccinations." (PMID 31008116, 2019).